FOXP3 (forkhead box P3)
Diseases named in the same sentence as FOXP3 in open-access papers (continued):
Sharing a sentence is not in itself a finding about the gene and the disease.
breast tumor (continued). "Similarly, induction of FoxP3+ Tregs also has been shown to promote 4 T1‐lung metastasis in breast tumor‐bearing mice and our data indicates upregulation of FoxP3 expression in the primary tumor, but not the lungs." (PMID 36325601, 2022). "To demonstrate the association between CCR4 and FOXP3 expression in core breast tumor tissue, we created a correlation coefficient plot, which further indicates that CCR4 expression is highly correlated with FOXP3 expression in breast tissue taken from different cohorts." (PMID 35222362, 2022). "Importantly, VAT Tregs, which are commonly decreased in obese mice, were significantly increased in the presence of breast tumors and displayed significantly higher levels of Foxp3, indicating a regulatory feedback mechanism triggered by tumor growth." (PMID 35472214, 2022). "Similarly, in our previous studies on bladder and breast tumors, we observed that the frequency of FOXP3+ Treg cells in the draining lymph nodes significantly increased in patients with tumor-affected nodes." (PMID 36038861, 2022). "SI-2 treatment significantly reduced the number of Foxp3 + Treg cells in E0771 breast tumors." (PMID 36316775, 2022). "Based on these reports, we believe that, in our case, FoxP3+ cell-infiltrates might be an indirect indicator of a preexisting antitumor immune response in breast tumors." (PMID 36551693, 2022). "Thus, FOXP3+ suppressive iTreg sharing TCR clones with Tconv in breast tumors possess protective machinery against FOXP3 methylation supporting their functional stability." (PMID 33602930, 2021). "CD8 and FOXP3 were higher in primary breast tumors than that in oligometastatic sites." (PMID 34858823, 2021). "Thus, breast tumors in frailer patients appeared to be more heavily infiltrated by immunosuppressive FOXP3+ cells." (PMID 33024560, 2020). "Furthermore, activation of the PI3K pathway, measured using phosphorylated downstream proteins, in breast tumor cells was positively correlated with tumor-infiltrating FOXP3-positive lymphocytes." (PMID 31391067, 2019). "Thus, this corroborates our in-vitro results by showing that tumor infiltrating pDCs derived from human breast tumors are capable of inducing more FoxP3+ CD4+ T cells, as well." (PMID 31440253, 2019). "Moreover, the dynamic range of FOXP3 expression in the breast tumor microenvironment is limited (0–15%)." (PMID 31391067, 2019). "Here, we report an augmentation CD8+FOXP3+ Tregs in breast tumor microenvironment." (PMID 28487507, 2017). "We also demonstrated that high CD8+ : FOXP3+ T cell ratios in the primary breast tumours and metastatic ALNs (tumour-free paracortex) were significantly associated with pCRs, highlighting the close and complex interrelationships between NAC and adaptive immunity." (PMID 28913366, 2017). "Furthermore, our data strongly suggests this interaction as a new tumor suppressor mechanism used by Foxp3 to reduce breast tumor promotion." (PMID 26735887, 2016). "Our work suggests for the first time that Runx1 could be involved in breast tumor progression depending on Foxp3 availability." (PMID 26735887, 2016). "Therefore, we further investigated the correlation between B7-H1+ TIL or PD-1+ TIL and FOXP3+ Tregs infiltration in breast tumors." (PMID 18294387, 2008). "Moreover, we observed and calculated the number of OCT4/SOX2/NANOG/FOXP3 positive cells per area taken from sections of the tumor tissues, and consequently found similar trend in stemness genes and FOXP3 coincides with high-grade of breast tumor compared to low-grade breast tumor (p < 0.0001)." (PMID 38038865, 2023). "In our second approach, Kaplan-Meier survival curve revealed lower probability of overall survival (OS) in breast tumor patients with higher CSC (NANOG) (p < 0.05) and Treg (FOXP3) (p < 0.05) signature genes, in concordance with earlier reports." (PMID 38038865, 2023).
breast tumor (continued). "In this study, we evaluated the frequencies of FoxP3+ and CD163+ cells in the TC and IM in primary breast tumors and found an accumulation in either of these areas which was associated with increased densities of CD8+ cells." (PMID 36551693, 2022). "In this study, we demonstrated that tumor necrosis factor receptor 2 (TNFR2) is highly expressed in both breast tumor tissue and tumor-infiltrating immunosuppressive CD4+Foxp3+ regulatory T cells (Tregs)." (PMID 34900985, 2021). "The baseline sTILs, FOXP3+ Tregs, and MPI in breast tumors can be used as predictive factors for the efficacy of NAC for BC patients." (PMID 32039020, 2019). "Although increases in FOXP3+ TILs infiltration and CCL20 expression have been revealed in several malignancies, their correlation in human breast tumors is as yet unclear." (PMID 31852159, 2019). "Significantly higher levels of Tregs (FOXP3+, CTLA-4+) and CD56+ NK cells were documented in ALN metastases than in the corresponding primary breast tumours." (PMID 29390966, 2018). "Then, to identify the developmental stages of CD8+ Treg cells in breast tumor microenvironment, we monitored the CD25- and FOXP3-positivity within CD8+ T cells." (PMID 28487507, 2017). "We also used immunofluorescence microscopy to analyze serial breast tumor sections stained for CD3 and CD4, and either CD45RA (naive CD4+ T cells) or Foxp3 (Tregs)." (PMID 28290464, 2017). "Both CD4 + /Foxp3 + and CD4-/Foxp3 + cells were detected in control E0771 breast tumors." (PMID 36316775, 2022). "The CD8+: FOXP3+ T cell ratio, on the other hand, was not significantly different between the primary breast tumours and the metastatic tumours in the ALNs." (PMID 29390966, 2018). "Recent evidence also suggests that the transcription factor FOXP3 directly binds to and inhibits RUNX1 in mammary epithelial cells, whereas in the absence of FOXP3 in breast tumors, RUNX1 downregulates Cx43 expression." (PMID 29701678, 2018). "Histologic examinations and expression analyses were made for five Foxp3+/+ wild-type mice, five Foxp3sf/+ mice without tumors, five mice with breast tumors only, and five mice with both breast tumors and lung metastases." (PMID 28637482, 2017). "Thus, the significant reduction in the circulating levels of Tregs in women with LLABCs undergoing NAC was associated with a substantial and significant concomitant reduction of FOXP3+ and CTLA-4+T cells infiltrating the breast tumours." (PMID 27777963, 2016). "The higher expression of CD8 and FOXP3 were in primary breast tumors than that in oligometastatic sites both in the intratumoral and peritumoral (primary vs oligometastatic tissue: CD8: the intratumoral P=0.031, the peritumoral P<0.001; FOXP3: the intratumoral P=0.039, the peritumoral P=0.012)." (PMID 34858823, 2021). "In a multivariable analysis high breast tumor median CXCL13 content was independently associated with favorable DDFS (HR 0.44, 95% CI 0.29–0.67; P ≤ 0.001), whereas CD4 content and FOXP3 content were not (HR 1.89, 95% CI 0.80–1.78; P = 0.396; and HR 1.20, 95% CI 0.78–1.84; P = 0.400, respectively)." (PMID 29482642, 2018). "However, mRNA expression of Foxp3 by qRT-PCR in 826 breast tumor tissue samples including 84 TNBC samples, was not significantly related to disease free survival (DFS), while none of the markers studied including CD3, CD8, and Foxp3 were of prognostic value for OS." (PMID 34283088, 2021). "Similarly, Gobert and colleagues found a strong correlation between infiltrating Foxp3+ Treg cells and CCL22, but not with CCL17, in breast tumor." (PMID 26020249, 2015).
lymphoma (57 papers, 2009 to 2026). A malignant (clonal) proliferation of B- lymphocytes or T- lymphocytes which involves the lymph nodes, bone marrow and/or extranodal sites. "In contrast, in relation to colorectal cancer and different lymphoma subtypes, a higher quantity of FoxP3+ Tregs is linked to improved survival outcomes." (PMID 39682197, 2024). "Nevertheless, in specific lymphoma subtypes, increased levels of FoxP3+ Tregs have been associated with conflicting survival outcomes." (PMID 39682197, 2024). "An increase in normal FOXP3+ Treg cells in dermal infiltrates of MF has been linked to improved prognosis, similar to other indolent lymphomas." (PMID 35642346, 2023). "Increased levels of CCL17 and/or CCL22 are also associated with higher frequencies of CD4+Foxp3+ T cells in cerebral spinal fluid of patients with lymphomatous and carcinomatous meningitis, gastric, and esophageal squamous cell carcinomas." (PMID 23874342, 2013). "This high CCL17/22 and FOXP3 mRNA expression in EBV+ epithelial tumors is reminiscent of that in EBV+ lymphomas, but this could be due to different underlying mechanisms." (PMID 35025968, 2022). "Moreover, the frequency of Foxp3+ Tregs in salivary gland tissues from SS patients correlated with the inflammation grade and some risk factors for the development of lymphoma." (PMID 33669065, 2021). "The distribution of CSF1R protein in tonsil was also compared, using double immunoenzymatic labelling technique, with other markers of the microenvironment known to be associated with lymphoma pathogenesis, for example, FOXP3, PD-1 and the cytotoxic marker Granzyme B." (PMID 26066800, 2015). "Studies have shown that the frequency of Foxp3 + regulatory T cells (Treg) in salivary glands may be correlated with glandular infiltration and the grade of local inflammation, while B cell activation is generally associated with an increased risk of lymphoma." (PMID 38376769, 2024). "Since forkhead box P3 (FOXP3) is a hallmark of regulatory T (Treg) cells, the expansion of FOXP3+ adult T-cell leukemia/lymphoma (ATL) cells is believed to contribute to immune suppression and the pathogenesis of ATL." (PMID 41305468, 2025). "Transgenic mice expressing the antisense viral gene HTLV-1 bZIP factor (HBZ) in CD4+ T cells develop lymphomas expressing Foxp3." (PMID 41305468, 2025). "Both lymphomas contained significantly more FOXP3+ Tregs, which was reflected in more CD4+FOXP3+CXCR5+PD-1+ TFR cells among CD4+ T cells, but not among Tregs for FL." (PMID 41030456, 2025). "One sample contained 30–40% positive cells (P43), one sample contained weakly expressed FoxP3+ (P68), and the remaining two samples (P2 and P75) contained strongly expressed FoxP3+ in all lymphoma cells." (PMID 39682197, 2024). "Out of 108 nodal PTCL patients included in the study, three cases were excluded due to them containing inadequate biological material, and four cases of PTCL-NOS (HTLV-1-negative) were excluded due to the expression of FoxP3 in lymphoma cells." (PMID 39682197, 2024). "This study finds fewer FoxP3+ cells in lymphoma subtypes such as nTFHL-F, advanced nTFHL-AI, and CL compared to reactive LNs." (PMID 39682197, 2024). "Accordingly, we detected FoxP3 expression only in the lymphoma cells from four HTLV-1-negative PTCL-NOS cases." (PMID 39682197, 2024). "As Foxp3 Tregs inhibit anti‐tumor response in endogenous lymphomas, ablation of Foxp3 Tregs significantly delays tumor progression." (PMID 39473905, 2024). "We found two cases with strong FoxP3 expression in the lymphoma cells, and this is consistent with the clinical presentation observed in published cases." (PMID 39682197, 2024). "In mature lymphomas, FoxP3+ Tregs constitute a significant component of the TME, and their quantity varies across B- and T-cell lymphoma (BCL and TCL) subtypes." (PMID 39682197, 2024). "FoxP3 expression in PTCL-NOS lymphoma cells is extremely rare, with few published cases showing aggressive progression and death shortly after diagnosis." (PMID 39682197, 2024).
lymphoma (continued). "The two other cases exhibited weak FoxP3 expression or expression in 30–40% of the lymphoma cells, both showing relatively short survival times." (PMID 39682197, 2024). "In contrast, the most significant decrease in FoxP3+ cell quantities in CLs compared to reactive LNs (p ≤ 0.001) was attributed to the simultaneous presence of two distinct types of lymphomas (nTFHLs-AI and BCLs)." (PMID 39682197, 2024). "As previously discussed, FOXP3+ Tregs are recruited to the TME through chemokine secretion by the lymphoma cells (including CCL5, CCL17, and CCL22)." (PMID 33804869, 2021). "Recent studies have shown that increased number of FOXP3 positive cells in the tumor microenvironment favorably affect the prognosis in different lymphomas including CHL." (PMID 32513132, 2020). "HTLV virus-related adult T cell leukemia/lymphoma shares a similar immunophenotype with Treg cells, with both displaying a high expression of FOXP3." (PMID 27589565, 2016). "We next investigated the distribution pattern of FOXP3+ cells in lymphoma and chronic gastritis samples." (PMID 23284739, 2012). "Our study provides further information on tumor-infiltrating FOXP3+ cells in lymphomas and other gastric conditions, in particular in gastric MALT lymphoma with special emphasis in response after therapy and in long term follow-up." (PMID 23284739, 2012). "In patients with different types of lymphomas, the percentage of tumor-infiltrating FOXP3+ T cells predicts different survival and prognosis." (PMID 22151904, 2011). "Finally, there was an equivalent increase in regulatory T cells (Tregs, CD4+FOXP3+) among mutant genotypes in the end-stage lymphomas, suggesting additional layers of immune dysfunction." (PMID 38570506, 2024). "In addition, the nuclei of FoxP3+-reactive T cells were substantially smaller and more common than those of the lymphoma cells." (PMID 39682197, 2024). "FOXP3 Tregs are found in various lymphomas as well as tumors." (PMID 35642346, 2023). "FoxP3-specific anti-Tregs recognize Tregs and kill malignant T cells expressing high FoxP3 levels, suggesting that vaccination against FoxP3 could be useful in patients with lymphoma involving FoxP3+ malignant T cells." (PMID 36175673, 2023). "Furthermore, data show a majority of adult T cell leukaemia/lymphoma cells which share the Treg phenotype, CD4+CD25+CCR4+FOXP3+, leading to the suggestion that adult T cell leukaemia/lymphoma cells are descendants of Tregs." (PMID 36794233, 2022). "Furthermore, CD70+ lymphoma B cells have been shown to partially contribute to Foxp3 expression in intratumoural CD4+CD25− T cells and thus the associated regulatory activity." (PMID 36471481, 2022). "FOXP3 is traditionally used as a marker of CD4+ regulatory T-cells (T-reg), which were already implicated on immune suppression and worse prognosis of other lymphoma subtypes, such as follicular lymphoma." (PMID 33648463, 2021). "In addition, CCR4 expression by MJ, a FoxP3-expressing adult T cell leukemia/lymphoma (ATLL) cell line, which highly expresses CCR427, was reduced by RNA interference-mediated knockdown of FoxP3 gene." (PMID 34907192, 2021). "TH2-polarized CD4+ T cells secrete cytokines that can limit CTL differentiation and proliferation such as IL-10 and IL-4, while CD4+ TRegs (FOXP3+) have significant immunosuppressive functions through various mechanisms and their pro-tumor role has been described in both solid tumors and lymphomas." (PMID 33842331, 2021). "In lymphoma, sIL-2Rα may present IL-2 in vitro to CD4 + T cells and cause the differentiation of these cells into FoxP3 + Treg cells, resulting in the suppression of CD8 + T cells." (PMID 32660627, 2020). "Therefore, to facilitate this analysis and future translational lymphoma research we followed others in employing single markers, either PD1hi or FOXP3+ as surrogates for Tfh and Treg subsets respectively." (PMID 30219078, 2018).
lymphoma (continued). "In attempting to interpret this subsequently, we noted that the lymphatic tissue of the palatine tonsils in chronic tonsillitis was characterized by the statistically significantly higher infiltration of CD25-positive cells and higher Foxp3 antigen immunoreactivity than in the lymphoma sample." (PMID 25773455, 2015). "We and others have recently characterised FOXP3+ Tregs in the dog, demonstrating that they have similar properties to those of human Tregs; we were thus optimally poised to interrogate their role in various canine diseases, including lymphoma." (PMID 25119018, 2014). "To test whether TGF-β was involved in the differentiation of T cells, we determined the effect of TGF-β on the generation of TH1 (CD4+IFN-γ+), TH17 (CD4+IL-17+) and Treg (CD4+Foxp3+) cells in lymphoma specimens." (PMID 23555036, 2013). "Moreover, intratumoral FOXP3+ T cells have been shown to migrate or be induced in response to chemokines produced by malignant B cells in some lymphomas." (PMID 23284739, 2012). "It has been shown that lymphoma-infiltrating FOXP3+ cells vary between different lymphoma types and these cells may represent important lymphoma/host microenvironment-modulators." (PMID 23284739, 2012). "Interestingly, the number of FOXP3+ infiltrating cells in gastric MALT lymphoma was more like chronic gastritis than transformed lymphomas." (PMID 23284739, 2012). "Lymphoma-infiltrating FOXP3+ cells may represent important lymphoma/host microenvironment-modulators, since increased number of these cells can positively influence survival in FL, germinal center (GC)-like DLCBL." (PMID 22151904, 2011). "FOXP3+ Treg density is varied in different lymphoma types and is highest in follicular lymphoma." (PMID 22151904, 2011). "Notably, the primary lymphoma cells expressed Foxp3 at various intensities in the majority of cases, exhibiting a similar FoxP3 staining pattern to that in lymph nodes in human ATL cases." (PMID 21347344, 2011). "Finally, adult T-cell leukemia/lymphoma cells from blood and skin tumors express FOXP3 at high levels but lack suppressor activity, suggesting that in these cells, despite their derivation from the immune system, the role of FOXP3 is unrelated to immune escape." (PMID 23888189, 2012). "Adult T-cell leukemia/lymphoma (ATLL) is an aggressive lymphoma associated with human T-lymphotrophic virus 1 (HTLV1) infection, and ATLL cells frequently express several molecules that are characteristic of Tregs, notably CD4, CD25, and the transcription factor FOXP3." (PMID 22151904, 2011). "The elevated proportion of CD4+FoxP3+PD-1+ Tregs in HIV-positive pre-NHL individuals likely reflects an adaptive response to chronic inflammation but may also serve as a mechanism that hampers effective HIV control, increasing the risk of lymphoma development in pre-NHL states." (PMID 41148820, 2025). "The lymphoma tissue blocks were labeled with primary antibodies against CD68, FOXP3, and CD8, followed by incubation with Alexa Fluor 488, Alexa Fluor 555 and Alexa Fluor 647 fluorescent secondary antibodies." (PMID 38164148, 2024). "In conclusion, in this study we found distinctly higher levels of expression of FoxP3 in AITL, PTCL-NOS, and ALCL when compared with previous studies of these lymphomas in immunocompetent individuals." (PMID 30856039, 2019). "In accordance with this finding, Toulza and colleagues have previously demonstrated that the concentration of CCL22 in adult T-cell leukemia/lymphoma patients was abnormally high and correlated with the frequency of CD4+FoxP3+ cells." (PMID 26020249, 2015). "Comparisons of respective FOXP3+ and CD8+ cells between the study groups yielded the initially surprising observation that dogs with lymphoma had lower frequencies of these cells than those with RH and MCTs." (PMID 25119018, 2014).